ARHGEF33 (Rho guanine nucleotide exchange factor 33)
Description:
May act as a guanine-nucleotide releasing factor.
Tractability: No criterion of Open Targets' tractability assessment is met for any kind of drug.
Gene: Protein-coding gene on chromosome 2 (38,889,875 to 38,975,454, forward strand). Ensembl gene ENSG00000214694.
Subcellular location (Human Protein Atlas): Vesicles; Cytosol; Nucleoplasm
Pathways (Reactome):
Signal Transduction: G alpha (12/13) signalling events; NRAGE signals death through JNK
Gene Ontology:
Molecular function: guanyl-nucleotide exchange factor activity
Genetic constraint (gnomAD): Loss-of-function variants: 54 observed, 71.55 expected, observed/expected ratio (o/e) 0.75, 90% interval 0.61 to 0.95. The upper end of that interval is the gene's LOEUF score, 0.95, which puts it in group 4 of 6, group 1 being the genes least tolerant of losing a copy. Missense variants: 939 observed, 835.59 expected, observed/expected ratio (o/e) 1.12, 90% interval 1.06 to 1.19. Synonymous variants: 417 observed, 353.48 expected, observed/expected ratio (o/e) 1.18, 90% interval 1.09 to 1.28.
Homologues: Orthologues: chimpanzee ARHGEF33 (99% identical), macaque ARHGEF33 (99% identical), dog ARHGEF33 (97% identical), pig ARHGEF33 (96% identical), rabbit ARHGEF33 (96% identical), guinea pig ARHGEF33 (90% identical), rat Arhgef33 (89% identical), mouse Arhgef33 (88% identical), tropical clawed frog arhgef33 (55% identical).
Diseases named in the same sentence as ARHGEF33 in open-access papers:
ARHGEF33 is named in the same sentence as 1 disease in open-access papers, as found by Europe PMC text mining. Sharing a sentence is not in itself a finding about the gene and the disease.
ARHGEF33 shares sentences with these, for which no sentence is quoted: adenoma (1 paper).